VDR (vitamin D receptor)
Diseases named in the same sentence as VDR in open-access papers (continued):
Sharing a sentence is not in itself a finding about the gene and the disease.
tumor (continued). "However, in advanced OSCC tumors, the expression of the VDR was significantly reduced, suggesting that as the tumor progresses, malignant cells may lose their ability to respond to vitamin D, thus facilitating their uncontrolled growth." (PMID 40282445, 2025). "Furthermore, the expression of VDR was affected by the degree of tumor differentiation." (PMID 38639057, 2024). "Therefore, it may be possible to use VDR agonists to reshape the tumor microenvironment for anti-tumor purposes." (PMID 38639057, 2024). "However, how VDR affects tumor progression through immunity remains to be determined." (PMID 38639057, 2024). "Additionally, the patients were tested for vitamin D receptor (VDR) and Toll-like receptor (TLR) gene polymorphisms in peripheral blood, as our previous studies have demonstrated the role of such polymorphisms in tumor development and progression." (PMID 37835512, 2023). "Next, the Vitamin D receptor can stimulate the proliferation and development of capillary-like tubules of endothelial colony-forming cells, and has been shown to inhibit developmental angiogenesis in the zebrafish larval eyes leading to abnormal tumor angiogenesis." (PMID 36817116, 2023). "In a clinical setting, a possible approach could be to use the resected tumor for PDO and/or cell line generation, while concomitantly testing VDR mRNA expression levels, as well as polymorphism state and performing an in vitro interrogation for calcitriol sensitivity of the derived cultures." (PMID 37958423, 2023). "However, prior investigations have suggested that in some cases more VDR expression in tumor cells might lead to a better prognosis and treatment response." (PMID 37520529, 2023). "Through the gene knockout vitamin D receptor (VDR), it was found that the loss of VDR expression did not promote the occurrence of the tumor, and did not affect the proliferation and progression of the tumor." (PMID 37020597, 2023). "Moreover, a deleterious effect could be masked if in some of the tumours, VDR signalling remained intact producing a marked beneficial effect." (PMID 35445563, 2022). "We hypothesized that vitamin D could indirectly regulate Th17 cell differentiation through the impact of VDR on OPN (OPN is known to regulate the expression of IL-17 through its receptors and OPN gene possesses VDR-responsive elements), and this could affect the progression of the tumor." (PMID 35954312, 2022). "Therefore, stromal JNK1 and VDR function as tumor suppressors in ESCC, and the degree of their stromal expression may affect the prognosis of ESCC." (PMID 36142861, 2022). "VDR belongs to the nuclear receptor superfamily of ligand-inducible transcription factors, which are active in a variety of physiological processes such as cell growth and differentiation, embryonic development, metabolic homeostasis, apoptosis, and metastasis of tumor cells." (PMID 35996514, 2022). "An animal experiment raises the effect of vitamin D via VDR on the development of the autonomic nervous system, so it may be possible that, like the healthy peripheral sympathetic nervous system, cells within the tumor mature that have VDR." (PMID 35884356, 2022). "Several studies have reported that high VDR may be an important response against tumor progression." (PMID 35099410, 2022). "The antiangiogenic effect of 1,25(OH)2D3 on tumor endothelial cells may also be VDR mediated." (PMID 34208589, 2021). "Hence, 1, 25 (OH)2D3 has been reported to inhibit proliferation and anti-tumor effects via VDR." (PMID 34881266, 2021). "Therefore, we postulate that there may be an effect of aPPD in enhancing calcitriol-mediated VDR activation and ultimately VDR-mediated tumor growth suppression." (PMID 34199743, 2021). "Also between high VDR expression in tumor cells and low grade (P= 0.09)." (PMID 33906311, 2021).
tumor (continued). "Investigation showed VDR positivity in 45.0 % of the triple-negative CMCs (TNCMCs), 27.3 % of luminal B and 19.0 % of luminal A. Luminal A was the most molecular subtype represented of the total tumours (36.2 %), followed of TNCMCs (34.5 %), luminal B (20.7 %) and HER2-overexpression (10.3 %)." (PMID 34034728, 2021). "Several explanations might contribute to explain the variable results of these studies such as polymorphisms in genes involved in 25(OH)D3 absorption, a variable expression of VDR at the tumor bed or the inability of 1,25(OH)2D3 to reach tumor site and exert its biological effects." (PMID 33780475, 2021). "In summary, the therapeutic use of this antihistamine with calcitriol could be beneficial as adjuvant therapy for BC, independently of the tumor phenotype, since the molecular targets of these compounds are the VDR and EAG1 channel, both of them highly expressed in BC." (PMID 34884550, 2021). "GC SNPs may influence the hormone tumor responsiveness and VDR may affect tumor prognosis." (PMID 33917614, 2021). "Furthermore, the acidic tumor microenvironment alters SOX2 in a VDR-dependent manner." (PMID 32900990, 2020). "Also, the exact roles of vitamin D receptor in different cell populations within breast tumors (adipose, endothelial, fibroblast, immune or epithelial), their interaction in normal and tumour tissue and in tumour microenvironment need to be clarified." (PMID 32679655, 2020). "Thus, although VDR stimulation may have an advantageous effect on the phenotype of pancreatic CAFs, a potential T cell mediated response against tumour cells may at the same time be dampened by vitamin D3." (PMID 33060625, 2020). "In addition, the TGF-β signalling pathway was related to VDR and 1,25(OH)2D, which were also detected in this study and could act as tumour suppressors." (PMID 29659618, 2018). "Therefore VDR may act as a tumor suppressor in presence of BRCA1mut and may potentially evolve as a promising new target in the future." (PMID 28427429, 2017). "The observation that vitamin D represses β-catenin signaling and that β-catenin activates the vitamin D receptor raise the possibility that impairment of the vitamin D pathway in vivo may affect the onset, incidence or progression of β-catenin-related neoplasias found in APC mutant mice." (PMID 27768599, 2016). "In addition, we measured the expression of a number of other genes in the tumours including nuclear receptors (VDR, RXRα, SXR, ER α and β), cytochrome P450 enzyme (CYP3A4), proliferation marker (MCM2, CDC6, KI67), differentiation marker (sucrase isomaltase) and angiogenesis marker (CD31)." (PMID 26238339, 2016). "Moreover, inflammatory peptides/cytokines expressed by tumour-infiltrating leucocytes and oral precancerous/tumor cells may upregulate VDR expression in adjacent cells." (PMID 25662556, 2015). "Our data do not rule out the presence of inactivating mutations in the VDR gene in these neoplasms." (PMID 24626468, 2014). "Variations in the dynamics of VDR nuclear translocation and its colocalization with RXRA, observed between tumor cells and healthy keratinocytes, guided the selection of optimal time points for transcriptomic investigations." (PMID 40724881, 2025). "For instance, the levels of angiogenic factors (such as HIF-1α, VEGF, etc.)increase in VDR knockout mice, while calcitriol can inhibit VEGF-dependent tumor growth in normal mice." (PMID 40705722, 2025). "Knocking down VDR in PC9/GR cells reduced cell viability and tumor growth, with the combination of VDR silencing and gefitinib treatment exhibiting a more pronounced effect than either intervention alone." (PMID 40872626, 2025).
tumor (continued). "For example, vitexin‐mediated activation of the Vitamin D receptor (VDR) has been shown to mitigate inflammation‐driven CRC progression, emphasizing the role of tumor microenvironment interactions in CRC development." (PMID 40165548, 2025). "In the Pan02 cell line overexpressing VDR, knockdown of CCL20 resulted in a deceleration of tumor cell proliferation in vivo and a reduction in the M2/M1 ratio." (PMID 38600588, 2024). "The set of parameters introduced for analysis included age of the subject, menopausal status, chemotherapy regimen, number of cycles, tumor-infiltrating lymphocyte density, Ki-67 expression, nuclear grade, HER2 status, ER and PR expression, and VDR-IRS." (PMID 39411136, 2024). "This study provides valuable insights into the function of the VDR in CESC, shedding light on the intricate relationship between vitamin D signaling, tumor biology, and the immune system." (PMID 39268267, 2024). "High expression of VDR in PAAD promotes M2 macrophage polarization and recruitment through the secretion of CCL20, which activates tumor progression." (PMID 38600588, 2024). "Vitamin D receptor (VDR) and its ligand Calcitriol have shown anti-tumor effects in various malignancies but to our knowledge there is no current information on VDR expression in bladder SCC." (PMID 38265102, 2024). "Triple-negative BC was more prevalent in subjects with higher values of both Δ nuclear VDR-IRS and Δcytoplasmic VDR-IRS (i.e., VDR-IRS for both nuclei and cytoplasm was higher in tumor cells than in normal cells)." (PMID 39411136, 2024). "PLA results on tumor tissue illustrated that the supplementation of VD3 promotes the interaction between YY1 and VDR at the tumor site, with a significant increase also observed in the interaction between VDBP and Twist1." (PMID 38164156, 2024). "TNM plot analysis revealed that both VDR and SIRT1 gene expression decreased from normal to tumour colonic tissue in a highly significant fashion (p<0.001)." (PMID 37530744, 2023). "We designed lentivirus-delivered VDR silencing and overexpression constructs in SW480 cells, detected the expression of key genes in Wnt/β-catenin signalling, and observed tumour growth in nude mice injected with VDR-OE SW480 cells." (PMID 37046222, 2023). "We also detected the expression of key genes involved in Wnt/β-catenin signalling (β-catenin, lymphoid enhancer factor (LEF)-1 and cyclin D1) in SW480 cells and nude mice injected with VDR-overexpressing SW480 cells and observed tumour development." (PMID 37046222, 2023). "The vitamin D receptors (VDR) are considered tumor suppressors in the skin which are the prime element of the Vitamin D endocrine system involving CYP27B1, CYP27A1, and VDR." (PMID 37803407, 2023). "It was found that calcitriol and VDR stimulate MEG3 and NAT2 gene expression in tumour cells through direct binding to their promoters." (PMID 37299554, 2023). "The genomic pathway responsible for vitamin D activity is regulated by vitamin D receptor (VDR), which is expressed in many tissues and numerous tumours." (PMID 36259314, 2022). "Stromal reprogramming with the vitamin A analogue, ATRA, or the vitamin D receptor agonist calcipotriol has shown promise, with both approaches promoting a quiescent PSC phenotype, reduced tumor fibrosis, and enhanced chemotherapy responses." (PMID 35081338, 2022). "Vitamin D and its metabolites, 1,25(OH)2D and vitamin D receptor (VDR), are closely related to tumour occurrence, development, and prognosis." (PMID 35807774, 2022). "However, the expression of VDR has been identified in many tissues in different cell types and the action of 1,25(OH)2D3 has important implications for regulating the immune system, where most cells express VDR, potentially influencing tumour immune surveillance." (PMID 35445563, 2022). "For example, it is feasible that tumour cells express less CYP24A1 as a result of a dysregulated and low VDR expression." (PMID 36362766, 2022).
tumor (continued). "In conclusion, the present study points to the role of VDR in the inhibition of DTC cell proliferation and tumor growth and the stimulation of DTC cell differentiation via the E-cadherin and β-catenin signaling." (PMID 35099410, 2022). "Treatment with vitamin A analogues or vitamin D receptor agonists to promote PSC quiescence, based on their physiological responsiveness to these nutritional stores, can suppress oncogenic signalling, tumour growth, and enhance chemotherapy response." (PMID 35533046, 2022). "Key pathways activated in neoplasias by BAs are regulated by nuclear receptors, FXR, CAR, SHP, PXR, LXR and VDR and other membrane receptors such as S1PR2, TGR5, CHRM2 and CHRM3." (PMID 35429253, 2022). "Another unexpected finding is the upregulation of VDR in both JIA and RA SF Treg cells, on both transcriptional and epigenetic level, as well as in tumor-infiltrating Treg cells." (PMID 33976194, 2021). "Genes of interest involved in tumor progression or uterine fibroids, from previous studies, FGFR1, CCND1, PCDH11X, VDR, NDRG2 and INPP4B, are indicated in the volcano plot." (PMID 33807176, 2021). "MEG3 (non-coding RNA maternally expressed gene) functions as a tumor suppressor in CRC by regulating the activity of clusterin, which is stimulated by the binding of vitamin D receptor to its promoter." (PMID 34218809, 2021). "Thus, the serum 25D concentration required to optimally activate VDR in tumor cells is unknown." (PMID 34950835, 2021). "Studies have shown that 1α, 25-(OH)2D and vitamin D receptor (VDR) in CRC cells stimulate MEG3 expression by directly binding to the promoter of lncRNA MEG3; MEG3 acts as a tumor suppressor by regulating clusterin activity." (PMID 33718238, 2021). "This relieves the inhibitory effect of VDR on the SOX2 promoter, thereby promoting SOX2 expression and leading to tumor growth and drug resistance." (PMID 32900990, 2020). "Menin, which is a putative tumor suppressor and an integral part of MLL1 and MLL2 histone methyltransferase complexes, has been suggested to directly interact with VDR and to enhance the transcriptional activity of the receptor." (PMID 32245092, 2020). "The results of the limiting dilution experiment in vivo showed that overexpression of VDR significantly inhibited tumor occurrence, whereas overexpression of SOX2 attenuated the repressive effect of VDR overexpression." (PMID 32900990, 2020). "Collectively, these data support the concept that VDR suppresses HAS2 and HA production in both normal mammary gland and in tumor cells in vivo." (PMID 32774770, 2020). "All these findings demonstrate that VDR inhibits the CSC phenotype and enhances the sensitivity of CRC stem cells to drugs in the acidic tumor microenvironment." (PMID 32900990, 2020). "In this study, we found that the acidic tumor microenvironment can reduce VDR expression via PPARD and prevent the accumulation of VDR in the nucleus." (PMID 32900990, 2020). "In summary, our data demonstrate that VDR and FOXP3 are expressed in CHL and that there is a direct correlation between VDR expression and quantity of FOXP3 expressing lymphocytes in CHL tumor microenvironment." (PMID 32513132, 2020). "Immunofluorescence staining showed the expression of VDR by primary Hodgkin’s (H) and Reed–Sternberg (RS)—HRS-tumor cells in HL histological sections." (PMID 30961641, 2019). "In therapy naïve ER-positive tumours our data suggest corepressor levels are high, perhaps to prevent LXR (and indeed other NRs such as VDR) from driving anti-proliferative transcriptional programs." (PMID 31683867, 2019). "Experimental evidence supports that the VDR signaling suppresses TGF-β-Smad2/3 signaling to attenuate the fibrotic reactions in fibrosis and tumor stroma." (PMID 31067787, 2019).
tumor (continued). "Calreticulin is a calcium-sequestering protein with a known ability to block VDR signal transduction by interacting with its DNA binding domain, which may explain the lack of antiproliferative activity of calcitriol observed in our cultured endothelial cells and in tumor endothelium." (PMID 31698751, 2019). "Specifically, a higher tumor expression of VDR in CRC correlates with a better prognosis, and there is a direct relation between the tumor differentiation level and VDR gene expression level." (PMID 29719581, 2018). "Here the vitamin D receptor serves as a regulator of PSC activation, and vitamin D receptor agonists revert PSCs to a quiescent state, reducing tumor fibrosis and enhancing delivery of chemotherapeutics." (PMID 30200666, 2018). "Because VDR was highly expressed on the HSCs relative to HCC cells, the observed therapeutic effect of calcipotriol inhibiting tumor growth likely results from suppressing activated HSCs." (PMID 30400797, 2018). "It is evident that the mRNA level of SPOP, VDR and SETD7 in CRC tissues is lower than in normal adjacent tissues, indicating the tumor suppressive roles of these genes and the poor differentiation of CRC." (PMID 30171794, 2018). "Measuring nuclear and cytoplasmic VDR expression in human tumors at different stages of progression and correlating these results with the patient's vitamin D status would help to clarify whether cytoplasmic accumulation of VDR might be relevant in regulating tumor growth in patients." (PMID 28460457, 2017). "The following marker genes were differentially expressed in the triphasic tumours relative to the blastemal tumours: PA (LHX1), RV/CSB/SSB (BMP2, CDH6, JAG1, PAPSS2), ePT and/or imHL (CIDEB, CLIC6, UNC5CL, VDR), and early DT/imHL (KCNJ1)." (PMID 29040332, 2017). "Furthermore, there has been limited attention directed at understanding how VDR integrates signaling between these diverse cell types and what soluble signals and paracrine pathways may be regulated by 1α,25(OH)2D3 in the tissue and tumor microenvironment." (PMID 24982636, 2014). "Among the most downregulated proteins, we found several confirmed or candidate tumour suppressor genes (eg, ID1, FAS, FPR1, IL10, PCGF2, VDR)." (PMID 25594007, 2014). "Blockage of versican V1 by shRNA knockdown, in tumor cells, inhibited TLR2/6, VDR, Cyp24, Cyp27B1, and hCAP18/LL-37 induction, as well as tumor cell proliferation and invasiveness." (PMID 23424670, 2013). "Only Factor 4AM can be seen as indication that progression to higher grades of malignancy makes its imprint on tissue out of the tumor area, as COX-2 and VDR in conjunction with tumor grading became salient." (PMID 24213465, 2012). "We present evidence that the VDR is a TCF/Lef independent transcriptional effector of the canonical Wnt pathway that promotes HF differentiation and modulates Wnt-induced tumour formation." (PMID 18213391, 2008). "Indeed, downregulation of PPARD reduced vitamin D receptor (VDR) expression and subsequently mitigated its inhibitory effect on the SOX2 promoter, thus promoting SOX2 expression and resulting in tumor growth and drug resistance of colorectal CSCs." (PMID 41148824, 2025). "Genome-wide studies of vitamin D receptor (VDR) target genes, as well as single-cell transcriptomic analyses of vitamin D-treated tumor tissues, may reveal differential responses across molecular subtypes." (PMID 41377467, 2025). "MSI analysis revealed significant positive correlations for TACC3 and CXCL1 (p < 0.05), suggesting their potential roles in MSI-high tumor biology, whereas ABCB1, TGFBI, and VDR lacked significant associations with MSI status." (PMID 40791849, 2025).